CAST (calpastatin )
Diseases named in the same sentence as CAST in open-access papers (continued):
Sharing a sentence is not in itself a finding about the gene and the disease.
infection (continued). "Notably, RT-qPCR analyses revealed a consistent increase in lnc-CAST expression at 24 h-post-infection (hpi) compared to the control." (PMID 38715098, 2024). "By 6 weeks post-infection the ∆bioA mutant had also been largely cleared from the lungs of CAST." (PMID 35112666, 2022). "In addition, CAST/EiJ mice showed the highest number of DEPS after infection in blood and lungs." (PMID 26921172, 2016). "Strikingly, infection of the “wild-derived” strains among CC founders, WSB, PWK and CAST, induced variable disease phenotypes for each strain." (PMID 39149485, 2024). "Caspase activation is inhibited in LVS infection by the concerted actions of XIAP, cIAPs and calpastatin." (PMID 35693822, 2022). "In the context of SARS-CoV, infection of various mouse strains (PWK/PhJ (PWK), CAST/EiJ (CAST), 129S1/SvImJ (129/S1), and WSB/EiJ (WSB) mice) appears to be associated with differential expression of several hundred lncRNAs." (PMID 36367091, 2022). "XIAP is maintained at high levels in LVS-infected PMNs via increased expression of the BIRC4 gene and by upregulation of calpastatin (CAST), which prevents calpain-mediated XIAP degradation in healthy cells and during LVS infection." (PMID 35873156, 2022). "At an increased infection dose of 2 × 103 FFU all mice from highly and intermediate susceptible strains (A/J, C57BL/6J, 129S1/SvImJ, NOD/ShiLtJ, CAST/EiJ and WSB/EiJ) succumbed to the infection." (PMID 26921172, 2016). "Some strains, such as 129S1/SvImJ and CAST/EiJ, had high levels of MA15 RNA on day 4 after infection whereas others, such as NZO/HILtJ and NOD/ShiLtJ, had low levels of MA15 RNA." (PMID 24902603, 2014). "Among mice infected with PR8 at day 2 after infection, IFNG was only expressed in C57BL/6J, CAST/EiJ, PWK/PhJ, and WSB/EiJ, whereas it was expressed in all strains except CAST/EiJ on day 4 after infection." (PMID 24902603, 2014). "To address this, we infected K18-hACE2 and CAST mice with 2×104 PFU of Beta VOC and 1 day post infection, mice were treated with a protease inhibitor (PF-1332) at 500 mg/kg/day or vehicle for the first 4 days of infection." (PMID 39149485, 2024). "The most notable change in a cellular population found in the CAST mice was an increase in the frequency but not the total cell number of interstitial macrophages, increasing over the course of infection, which was not seen in B6J or K18-hACE2 mice." (PMID 39149485, 2024). "Interestingly, Wfdc17 was up-regulated in lungs of C57BL/6J, 129S1/SvlmJ and PWK/PhJ after infection, but not in CAST/EiJ which is consistent with the observed increase of infiltrating macrophages in CAST/EiJ lungs." (PMID 26921172, 2016). "Also, the Wfdc17 gene, encoding the AMWAP protein (activated microglia/macrophage whey acid protein domain protein), was not expressed in CAST/EiJ mice before and after infection." (PMID 26921172, 2016). "However, compared with the mock-GRV-infected cells, the expression of full-length (FL) calpastatin-GRV in infected CD4+ T cells was not maintained, and the positive cells had almost disappeared by day 7 after infection." (PMID 22046434, 2011).
neurodegenerative disease (6 papers, 2018 to 2026). A disorder of the central nervous system characterized by gradual and progressive loss of neural tissue and neurologic function. "The protective effects of calpain inhibition via the genetic enhancement of CAST have been observed in several other neurodegenerative diseases, such as AD, PD, and ALS." (PMID 34489447, 2021). "Engaging this system with pharmacological tools such as specific calpain inhibitors or compounds targeting activating pathways as well as genetic strategies, like overexpressing CAST or ablating calpain isoforms, showed phenotype-attenuating effects in models of neurodegenerative diseases." (PMID 35482253, 2022). "In the light of this study, the suggestive therapeutic strategy might be the prevention of the degradation of Calpain-CAST complexes and the inhibition of Calpain for the treatment of neurodegenerative diseases such as AD." (PMID 29875647, 2018). "Calpain inhibition by overexpression of CAST or pharmacological means has been proven effective in reducing levels of toxic fragments and aggregates of mutant proteins, thereby attenuating the overall pathology in models of neurodegenerative diseases including HD, MJD and PD." (PMID 35482253, 2022). "Further investigations on how the CAST–calpain–Drp1 cell death pathway is controlled and how the biological optimization of CHIR99021 may accelerate the discovery of therapeutic approaches to treat multiple neurodegenerative diseases are warranted." (PMID 34489447, 2021).
neurological disease (4 papers, 2017 to 2025). "While its protective role in calpastatin in cardiovascular and neurological disease is established.emerging evidence links abnormal calpastatin-mediated Ca2+ regulation to PE." (PMID 41162732, 2025). "Future studies will resolve the molecular interactions and signaling pathways by which CAST/ELKS regulate VGCCs and synaptic transmission in different synapses and their roles in neuronal circuit function and impact on neurological diseases." (PMID 29996090, 2018).
nephropathy (2 papers, 2016 to 2020). A nonspecific term referring to disease or damage of the kidneys. "Thus the severity of kidney disease increased with the number of CAST alleles in Tg-Sub-III and Tg-Sub-IV mice, demonstrating an additive effect (nonparametric p-value = 9x10—65x10-3)." (PMID 27736906, 2016).
metabolic disease (1 paper, 2024). A congenital disorder (due to inherited enzyme abnormality) or acquired (due to failure of a metabolically important organ) disorder resulting from an abnormal metabolic process. "For example, unlike C57BL/6 J mice, WD-fed A/J, BALB and CAST are often protected against hallmarks of WD-induced metabolic disease." (PMID 38961153, 2024).
CAST also shares sentences with these, for which no sentence is quoted: acute myelogenous leukemia (2 papers); amyloid (2); Hypertension (2); Insulin resistance (2); pancreatic adenocarcinoma (2); acute kidney injury (1); ankylosing spondylitis (1); Arthritis (1); autoimmune disorders (1); autosomal recessive congenital ichthyosis (1); B cell lymphoma (1); bradyopsia (1); cancers of the bile duct (1); cerebral amyloid angiopathy (1); citrullinemia (1); colitis (1); cone-rod dystrophy (1); congenital stationary night blindness (1); corneal dystrophy (1); dilated cardiomyopathy (1); dyskeratosis congenita (1); ectodermal dysplasia (1); endotoxemia (1); gastrointestinal tumors (1); glaucoma (1); glomerulosclerosis (1); Hearing impairment (1); heart disease (1); Hepatic fibrosis (1); ichthyosis vulgaris (1).
A further 36 diseases each share a sentence with CAST in 1 paper.